MIR137HG (MIR137 host gene)
Gene: Long non-coding RNA gene on chromosome 1 (97,933,474 to 98,054,717, reverse strand). Ensembl gene ENSG00000225206.
Gene Ontology:
Biological process: miRNA-mediated post-transcriptional gene silencing
Cellular component: RISC complex
Diseases named in the same sentence as MIR137HG in open-access papers:
MIR137HG is named in the same sentence as 5 diseases in open-access papers, as found by Europe PMC text mining. Sharing a sentence is not in itself a finding about the gene and the disease. The quoted sentences say what the papers report.
atherosclerosis (1 paper, 2023). A disease characterized by the build-up of fatty material and calcium deposition in the arterial wall resulting in partial or complete occlusion of the arterial lumen. "Molecular docking revealed most DSY bioactive components can bind key EndMT-related lncRNAs, including AC003092.1, MIR181A1HG, MIR155HG, WEE2-AS1, and MIR137HG, suggesting DSY may mitigate EndMT in atherosclerosis by modulating the ceRNA network." (PMID 38268851, 2023).
gastric cancer (1 paper, 2022). A primary or metastatic malignant neoplasm involving the stomach. "The function results in vivo and in vitro were coincident with expression data, which indicated that MIR137HG played an oncogene in gastric cancer." (PMID 35733138, 2022). "According to the results in vivo, MIR137HG could promote gastric cancer cell colony formation, migration, and invasion in the gastric cancer cell lines." (PMID 35733138, 2022).
tumor (2 papers, 2022 to 2025). "patients with higher MIR137HG expression intending to lead to the poor differentiation tumor." (PMID 35733138, 2022).
MIR137HG also shares sentences with these, for which no sentence is quoted: cancer (1 paper); neuroblastoma (1).